KRTAP3-2 (keratin associated protein 3-2)
Description:
In the hair cortex, hair keratin intermediate filaments are embedded in an interfilamentous matrix, consisting of hair keratin-associated proteins (KRTAP), which are essential for the formation of a rigid and resistant hair shaft through their extensive disulfide bond cross-linking with abundant cysteine residues of hair keratins. The matrix proteins include the high-sulfur and high-glycine-tyrosine keratins.
Synonyms: KAP3.2; KRTAP3.2
Tractability: No criterion of Open Targets' tractability assessment is met for any kind of drug.
Gene: Protein-coding gene on chromosome 17 (40,999,193 to 40,999,906, reverse strand). Ensembl gene ENSG00000212900.
Pathways (Reactome):
Developmental Biology: Keratinization
Gene Ontology:
Molecular function: protein binding; structural molecule activity
Cellular component: cytosol; keratin filament
Genetic constraint (gnomAD): Loss-of-function variants: 2 observed, 5.73 expected, observed/expected ratio (o/e) 0.35, 90% interval 0.14 to 1.1. That is too few expected variants to judge how well the gene tolerates losing a copy. Missense variants: 113 observed, 125.01 expected, observed/expected ratio (o/e) 0.9, 90% interval 0.77 to 1.06. Synonymous variants: 49 observed, 48.91 expected, observed/expected ratio (o/e) 1, 90% interval 0.8 to 1.27.
Homologues: Orthologues: chimpanzee KRTAP3-3 (98% identical), mouse Krtap3-2 (84% identical), mouse Krtap3-3 (84% identical), rat Krtap3-2 (84% identical), rat Krtap3-3 (84% identical). Paralogues in human: KRTAP3-3 (98% identical), KRTAP3-1 (74% identical), KRTAP24-1 (37% identical).